ROS1 (ROS proto-oncogene 1, receptor tyrosine kinase)
Diseases named in the same sentence as ROS1 in open-access papers (continued):
Sharing a sentence is not in itself a finding about the gene and the disease.
pneumothorax (1 paper, 2024). Abnormal presence of air in the pleural cavity. "Notably, in 20 normal lung tissues form pneumothorax patients, the AmoyDx detected KRAS G12C mutation (n = 1) and ROS1 fusion (n = 1)." (PMID 38816489, 2024).
rectal cancer (1 paper, 2025). A primary or metastatic malignant neoplasm that affects the rectum. "NTRK alterations (NTRK1/2/3) were present in 0.9% and 0.5%, ROS1 alterations in 0.4% and 0.2%, RET alterations in 0.6% and 0.4%, and ALK alterations in 0.5% and 0.4% of samples in colon and rectal cancer, respectively." (PMID 39865537, 2025).
serous carcinomas (1 paper, 2023). "The RAS-MAPK signaling pathway (genomic alterations of NF1 at 16% and KRAS at 12% with mutual exclusivity), the PI3K-mTOR pathway (PIK3CA at 12% and TSC2 at 8%), and certain receptor tyrosine kinases (ROS1 at 9% and ERBB2 at 8%) might be candidates for targeted therapy in serous carcinomas." (PMID 38201563, 2023).
squamous cell carcinoma of the vulva (1 paper, 2025). "This retrospective study examined the clinical significance and prognostic value of ROS1 expression on immunohistochemistry in vulvar squamous cell carcinomas." (PMID 40847660, 2025). "The evidence linking squamous cell carcinoma of the vulva (VSCC) and ROS1 expression is scarce." (PMID 40847660, 2025).
systemic lupus erythematosus (1 paper, 2024). An autoimmune multi-organ disease typically associated with vasculopathy and autoantibody production. "Furthermore, the identification of the enriched systemic lupus erythematosus (SLE) signature might be related to the higher risk of thromboembolic events in ROS1+ NSCLC patients." (PMID 39737401, 2024). "The identification of the enriched systemic lupus erythematosus (SLE) signature in ROS1+ NSCLC might be a priori a puzzling finding." (PMID 39737401, 2024).
thymoma (1 paper, 2017). A neoplasm arising from the epithelial cells of the thymus. "A weak ROS1 reactivity by immunohistochemistry was noted in three (20 %) type A thymomas, however, they did not harbor a ROS1 translocation as assessed by FISH." (PMID 27844328, 2017). "A low ROS1 expression was present in 3 (20 %) of 15 type A thymomas, but none of them harbored a ROS1 gene translocation as assessed by FISH (data not shown)." (PMID 27844328, 2017).
tumor (413 papers, 2011 to 2026). "ROS1 mutation status, tumor mutational burden (TMB), neoantigen load, immune cell infiltration (via CIBERSORT), and immune-related gene expression were evaluated." (PMID 40873541, 2025). "By constitutively activating the ROS1 kinase domain, these chimeric proteins drive tumor growth and are linked to a more aggressive clinical course, giving them both diagnostic and prognostic weight." (PMID 40868080, 2025). "In ALK-negative tumours, alternative drivers have been identified, including ROS1, RET, NTRK3 and PDGFRB rearrangements or mutations." (PMID 40980125, 2025). "In the ROS1 mutation group, 16 patients (62.5%) developed tumor metastasis, and lung metastasis (5 cases, 31.3%, P = 0.045) and pleural metastasis (6 cases, 37.5%, P = 0.044) often occurred." (PMID 39464712, 2024). "We proposed that tumor heterogeneity is the underlying reason for the secondary ROS1 rearrangement observed in patients." (PMID 39723367, 2024). "Co-treatment with IN10018 and ROS1 inhibitors significantly reduced the tumor size in CDX models and PDX models with CDH1 deficiency." (PMID 37324948, 2023). "Co-administration of the FAK inhibitor IN10018 enhances the anti-tumor effect of ROS1 inhibitors in the treatment of CDH1-deficient cancers." (PMID 37324948, 2023). "Molecular testing using the circulating tumor DNA (ctDNA) NGS assay identified a ROS1 F2004V kinase domain resistance mutation." (PMID 37291202, 2023). "Transcriptomics indicates that DICER1 tumors are RAS-like, whereas the ROS1-mutated tumor displays a borderline RAS-/BRAF-like subtype." (PMID 37867524, 2023). "Second, we excluded ROS1 mutations from tumor samples that harbored > 15 total alterations (> 15 total mutation burden for samples where we had this information)." (PMID 37587872, 2023). "The results showed that ROS1 gene mutations, tumor stage, and the endocrine system diseases history were independent adverse prognostic factors, while KRAS gene mutations were independent prognostic protective factors." (PMID 37468609, 2023). "The liquid-based analysis identified 2 ROS1 mutations, whereas the tissue-based analysis detected only one (in the other case, an insufficient tumor sample prohibited the analysis)." (PMID 35785173, 2022). "More exceptionally, ROS1-rearranged tumours treated with crizotinib or entrectinib can have a resistance mechanism detected in cf-DNA, notably a ROS1 mutation." (PMID 35456982, 2022). "Studies have shown that somatic chromosomal fusions involving ROS1 generate chimerical tumor proteins that can cause various cancers." (PMID 35140786, 2022). "The presence of PIK3 mutation and ROS1 mutation also had a statistically significant favorable impact on the best overall radiologic tumor response while with FGFR mutation, this trended toward statistical significance." (PMID 33619913, 2021). "Elevated tumor mutational burden and enrichment of DNA damage repair was observed in ROS1 mutated patients, providing an explanation for the favorable responses to ICI therapy." (PMID 34221982, 2021). "By carefully outlining every ROS‐1‐mutated tumor, larger amounts of data will be gathered to gain even more insight into the tumor biology and molecular behavior in this specimen of oncogene‐addicted NSCLC." (PMID 31799812, 2020). "Potential examples of such tumor-agnostic targets other than NTRK include (but not limited to) ALK, BRAF, BRCAness, FGFR, HER2, HER3, homologous recombination deficiency (HRD), KRAS, RET, ROS1, tumor mutation burden (TMB) high." (PMID 31974683, 2020).
tumor (continued). "published on 30 March 2020, which shows that ROS1 fusion primary NSCLC tumor was significantly associated with the up-regulation of PD-L1 expression." (PMID 33324391, 2020). "Response here is significantly longer than that observed in ALK positive tumours, partly due to the natural history of ROS-1 mutated tumours, which tend to run a more indolent course." (PMID 30021993, 2018). "Prerequisites for enrolling in this trial include advanced solid tumors containing ROS1 or NTRK gene rearrangements or advanced solid tumors causing tumor-induced pain." (PMID 29617282, 2018). "The study found that crizotinib also has a good anti-tumor effect on patients with NSCLC rearranged gene encoding proto-oncogene receptor (ROS1), the FDA approved in March 2016 its scope of application to broaden to ROS1-positive NSCLC patients." (PMID 29455664, 2018). "Molecular alterations including KRAS mutations, EGFR mutations, and ALK/ROS1 re-arrangements were detected in 23.2%, 19.6%, and 5.4% of analyzed tumor samples, respectively." (PMID 29707129, 2018). "FISH analysis of tumor specimens for diagnostic testing of biomarkers such as ALK- or ROS1-rearrangement is in most cases still done manually by cytogeneticists." (PMID 27417942, 2016). "Although the frequency of mutations in ROS1 is low in patients, the significant tumour control obtained with crizotinib indicates that NSCLC patients should be tested for ROS1 rearrangements." (PMID 27350784, 2016). "The mechanisms underlying such acquired ROS1 alterations remain unclear but may relate to tumor heterogeneity, genomic instability and selective pressures induced by cytotoxic and targeted therapies." (PMID 40371229, 2025). "Additionally, further research to unveil the mechanisms that result in a poor response to immunotherapies beyond the already known low tumor mutational burden (TMB) of ROS1 + NSCLC." (PMID 38433235, 2024). "Notably, most ROS1-positive tumors exhibit low PD-L1 expression and have a low tumor mutation burden (TMB)." (PMID 38927911, 2024). "In addition, KRAS G12D mutations and C-Ros oncogene 1 (ROS1) rearrangement were likely to be present in one tumor simultaneously." (PMID 37284902, 2023). "In this study, we hypothesized that a subset of ROS1 nonsynonymous missense mutations could be gain‐of‐function variants contributing to tumor formation and responsive to treatment with TKIs." (PMID 37587872, 2023). "Unexpectedly, when we further detected whether the neoplasm cells of ES-RMS exist ROS1 mutation, we firstly found tumor cells showed not only ROS1 mutation but also increased copy numbers." (PMID 36998041, 2023). "In addition, KRAS G12D mutations and C-Ros oncogene 1 (ROS1) rearrangement were likely to be present in one tumor at the same time." (PMID 37284902, 2023). "To address this hypothesis, we interrogated the AACR Genie dataset to identify ROS1 missense variants in a tumor‐agnostic manner." (PMID 37587872, 2023). "ALK and ROS1 kinases demonstrate significant similarities with regard to amino acid sequence, mode of genetic alterations, the spectrum of associated tumor types, correlations with clinical characteristics of cancer disease, and patterns of sensitivity to tyrosine kinase inhibitors." (PMID 35322575, 2022). "Besides ATR mutations, common mutated genes (BRCA1, EGFR, and ROS1) that characterize LUAD were also found in 5 tumor samples." (PMID 35712480, 2022). "However, ROS1 translocation tends to be associated with a higher stage and higher tumor grading in both the pre-crizotinib stage and the post-crizotinib stage." (PMID 35628598, 2022). "ROS1 mutation was correlated with elevated tumor antigenicity and genomic instability." (PMID 34221982, 2021). "In order to study the mechanisms that may potentially be associated with the impairment of KL-ROS1 tumor growth that was observed in wt mice vaccinated against ROS1, we investigated the immune response induced by the electrovaccination." (PMID 32268572, 2020).
tumor (continued). "With this in mind, we have focused on the c-ros oncogene 1 receptor tyrosine kinase (ROS1), an orphan tyrosine kinase receptor whose aberrant activation has been implicated with enhanced tumor cell growth, proliferation, metastasization, and resistance to chemotherapy." (PMID 32268572, 2020). "For patients with EGFR mutation-positive, ALK rearrangement-positive or ROS1 rearrangement positive tumours first-line molecular targeted tyrosine kinase inhibitors are recommended, while patients with high PD-L1 expression in the tumour are suitable for pembrolizumab first-line treatment." (PMID 31088547, 2019). "We agree it is difficult to draw certain conclusions given the evidence of today, though in our opinion, different driver mutations (such as EGFR or KRAS mutations or ALK or ROS1 rearrangements, like in our cases 4 and 6) probably quite strongly support synchronous/metachronous tumours." (PMID 28347348, 2017). "The pathogenic role of ROS1 is suggested in these specific tumor types as in BTCs." (PMID 26475437, 2015). "Several studies have shown that in NSCLC cells with gene alterations of KRAS G12C, BRAF V600E, EGFR, ALK, or ROS1, dysregulation of the Hippo pathway decreases the initial response to various tyrosine kinase inhibitors, which is associated with resistance of targeted therapy and tumor recurrence." (PMID 38499647, 2024). "However, it remains unclear whether ROS1 missense mutations or amplifications can independently drive or contribute to tumor development." (PMID 37587872, 2023). "In ROS1-Mut tumors, genes associated with the MYC signaling pathway were significantly upregulated, mediating tumor proliferation, metabolic adaptation, and immune evasion." (PMID 40873541, 2025). "One tumor had only a point mutation in NTRK1, while the remaining tumor showed 11 heterozygous deletions, including in ROS1, BCLAF1, and ARID1B, which were frequently altered in the entire cohort." (PMID 40227833, 2025). "For unresectable or recurrent ALK/ROS1 fusion–positive tumours, targeted tyrosine kinase inhibitors, such as alectinib, can be beneficial." (PMID 41368177, 2025). "Mechanistically, ROS1-mutant tumors displayed an immunosuppressive tumor microenvironment characterized by diminished CD8+ T cell infiltration, attenuated interferon-γ signaling, and downregulation of immune-related genes (CXCL9, CXCL10, IFNG, PD-L1)." (PMID 40873541, 2025). "ALK and ROS1 are involved in chromosomal rearrangements that result in the production of constitutively active, tumor-driving receptor tyrosine kinases, and patients with ALK or ROS1 fusions are recommended specific targeted therapies." (PMID 40739404, 2025). "Clinical variables assessed included demographic data, comorbidities, Eastern Cooperative Oncology Group (ECOG) performance status, tumor characteristics, genetic mutations (EGFR, ALK, ROS1), treatment responses, toxicity profiles, and survival outcomes." (PMID 40805843, 2025). "The oncogenic signaling pathway mutations consisted of KRAS, EGFR, and ALK/ROS1/RET mutations, which play crucial roles in cell proliferation and are associated with tumor aggressiveness and a higher risk of recurrence." (PMID 40507370, 2025).
tumor (continued). "These TKIs bind to the ROS1‐fusion protein, inhibiting its phosphorylation activity on downstream proteins and suppressing tumor growth." (PMID 40878657, 2025). "The genomic landscape of Spitz neoplasms includes fusions in genes such as ALK, ROS1, MET, RET, or BRAF and mutations in HRAS genes, which influence both the tumor’s biological behavior and morphological features." (PMID 40870546, 2025). "In the first case, fluorescence in situ hybridization (FISH) revealed a ROS1 rearrangement in 7 out of 50 tumor cells (14%)." (PMID 40575627, 2025). "Fluorescent in situ hybridization (FISH), immunohistochemistry (IHC), and sequencing of DNA and RNA are standard methods to detect ALK and ROS1 fusions, but they are costly, time-consuming, and require adequate tumor tissue." (PMID 40739404, 2025). "High-attention areas primarily correspond to regions dense with invasive tumor cells, reflecting their biological relevance in predicting ROS1 fusion status." (PMID 40739404, 2025). "This study identified 56 ROS1+ NSCLC tumor samples over the past 10 years, with clinical data available for 50 patients." (PMID 40878657, 2025). "Patients with tumors showing EGFR, ALK or ROS1 gene alterations were excluded, and the PD-L1 tumor proportion score was determined." (PMID 38539510, 2024). "Surprisingly, at the time of the progression on pemetrexed, a ROS1 translocation was found by FISH (39% of the tumour cells with a split signal) upon molecular NSCLC retesting." (PMID 38891886, 2024). "The degrader can effectively inhibit ROS1-dependentcell proliferation and tumor growth by degrading the ROS1 kinase,thereby eliminating the active phospho-ROS1." (PMID 39361251, 2024). "One of four patients with a ROS1 fusion–positive tumor responded (24%), namely a patient with LGSOC." (PMID 38938274, 2024). "The transcriptomic characteristics of ROS1+ non-small cell lung cancer (NSCLC) represent a crucial aspect of its tumor biology." (PMID 39737401, 2024). "Although no genes regulated through the Notch signaling pathway were significantly dysregulated, we found that NOTCH1 expression decreased significantly in ROS1+ tumor samples compared to RET+ specimens (p=0.04)." (PMID 39737401, 2024). "The resulting Cq values for the QfusionTM ALK, RET, or ROS1 fusion assays at a 15% tumor fraction were determined as 32.45 ± 0.17, 28.84 ± 0.25, and 25.27 ± 0.03, respectively." (PMID 38472960, 2024). "ROS1, a member of the sevenless subfamily of tyrosine kinase insulin receptors, promotes tumor cell survival, proliferation, and metastasis by activating the JAK/STAT, PI3K/AKT, and MAPK/ERK pathways." (PMID 39723367, 2024). "Break-apart ROS proto-oncogene 1 (ROS1) FISH was positive for ROS1 translocation (split signals in 39% of tumour cell nuclei)." (PMID 38891886, 2024). "The highest overexpressed gene in ROS1+ tumor specimens and cell lines, ISL1 provides new insights about this molecular subtype." (PMID 39737401, 2024). "The prolonged use of ROS1 inhibitors often leads to the development of drug resistance in tumor cells during disease progression." (PMID 38629293, 2024). "The fusion of ROS1 can lead to autophosphorylation, mediating tumor progression through the mitogen‐activated protein kinase (MAPK) pathway or RAS phosphorylation." (PMID 38629293, 2024). "The trait that defines this gene cluster is the comparison between ROS1+ tumor specimens and normal or healthy lung samples." (PMID 39737401, 2024). "ROS1 rearrangements, found in 1−2% of NSCLC patients, are identified as oncogenic drivers, creating a distinct molecular subgroup of NSCLCs since it is rare for ALK and ROS1 rearrangements to occur in the same tumor." (PMID 39335535, 2024).